RNU4ATAC16P (RNA, U4atac small nuclear 16, pseudogene)
Gene: Small nuclear RNA gene on chromosome 12 (781,133 to 781,258, forward strand). Ensembl gene ENSG00000221439.
Homologues: Orthologues: chimpanzee RNU4ATAC16P (100% identical). Paralogues in human: RNU4ATAC2P (87% identical), RNU4ATAC18P (86% identical), RNU4ATAC11P (83% identical).